KMT2D (lysine methyltransferase 2D)
Diseases named in the same sentence as KMT2D in open-access papers (continued):
Sharing a sentence is not in itself a finding about the gene and the disease.
lymphoma (continued). "Previously published studies pointed out that the deficiency and mutations in KMT2D could hinder B cell differentiation and delay germinal central degeneration, thus resulting in rapid progression and high mortality with lymphoma." (PMID 35937947, 2022). "As epigenetic regulators, KMT2D mutations are common in lymphoma." (PMID 35740649, 2022). "KMT2D is a known tumour suppressor, and mutations are common in lymphoma." (PMID 36580499, 2022). "However, H3K4me3 demethylation caused by the loss of KMT2D function in the germinal center of lymphoma led to rapid tumor progression, and the re-establishing of H3K4 trimethylation caused significant tumor growth inhibition." (PMID 35392225, 2022). "Taken together with our transcriptional profiling showing enrichment for Tet2 and Kmt2d deficient signatures, these data suggest that reduced levels of Smc3 in lymphomas impairs expression and functionality of tumor suppressor genes through disruption of enhancer-promoter interactions." (PMID 34621263, 2021). "However, in mice with both loss of Kmt2d and deregulated Bcl2 expression, lymphoma incidence increased from 44.4% (12/27) in wild-type mice to 62.5% (15/24) in heterozygous mice and 78.6% (22/28) in homozygous mice, with cases ranging from early FL to DLBCL98." (PMID 33277464, 2020). "We show that mutant-EZH2 elicits extensive effects on the epigenome of lymphomas, beyond alterations to H3K27 methylations, and is epistatic over KMT2D mutations." (PMID 40504770, 2025). "Next to genomic aberrations affecting epigenetic modifiers, such as EZH2, KMT2D, and CREBBP, transcription in is also rewired in GC-derived lymphomas via mutations in the gene encoding the transcription factor MEF2B." (PMID 38124747, 2023). "KMT2D suppressed lymphoma by activating pro-apoptotic genes while repressing genes associated with cell growth and survival pathways, such as cell cycle and anti-apoptotic genes." (PMID 34194626, 2021). "KMT2D mutations, which impair KMT2D/MLL2 protein function in mediating H3K4 mono- and di-methylation, have been reported as an early event in lymphoma development." (PMID 33260693, 2020). "Those who received HPCs with knocked-down Kmt2d expression in addition to increased Bcl2 expression exhibited early onset of lymphoma, splenomegaly, and histopathological evidence of high-grade FL." (PMID 33277464, 2020). "Their loss‐of‐function was reported to rescue repression of KMT2D target genes in KMT2D‐mutant lymphoma cells and selectively suppress the growth of these cells in vitro and in vivo." (PMID 30874354, 2019). "However, KMT2D can also interfere with the development of B cells and promote the development of lymphoma, lung cancer, and breast cancer." (PMID 39867575, 2024). "Conversely, Kmt2d deficiency was variably associated with a lack of cancer development or with the development of non-GC aggressive lymphomas, depending on inactivation strategy, i.e. Cγ1creKmt2dfl/fl mice or CD19creKmt2dfl/fl mice, respectively." (PMID 38022603, 2023). "Conditional deletion of Crebpp or Kmt2d in mouse B cells results in GC hyperplasia and increases the incidence of GC lymphoma in BCL2-driven mouse models after iterative SRBC immunization, with a spectrum of histopathological features ranging from early FL to DLBCL." (PMID 38022603, 2023). "Also, evidence has shown that KMT2D functions as a tumor suppressor and that its genetic ablation in B cells promotes lymphoma development in vivo." (PMID 35646048, 2022). "However, recent studies have also found that KMT2D can inhibit the development of medulloblastoma, lung tumors, and lymphoma, by activating particular pro‐apoptotic genes or repressing genes related to cell growth and survival." (PMID 35486034, 2022).
lymphoma (continued). "Conditional knock-out alleles have been successfully employed to study the in vivo role of many lymphoma-associated tumor suppressor genes encoding for transcription factors (BLIMP1), epigenetic modifiers (EZH2, CREBBP, KMT2D, TET2), small G proteins (GNA13) and ubiquitin ligases (FBXO11)." (PMID 34456919, 2021). "Interestingly, pharmacological inhibition of the KDM5 family of H3K4 demethylases diminished tumorigenic growth of KMT2D-mutant lymphoma cells, as certain KDM5 family members can antagonize the function and methylation activity of KMT2D." (PMID 34194626, 2021). "The link between KMT2D and glycolysis may be relevant and worth to explore in detail in lymphoma, as glycolysis measured by expression of aldolase A and GAPDH was associated with significantly shorter transformation-free survival in FL patients." (PMID 35071240, 2021). "In additional, Kmt2d knockdown in VavP-BCL2 hematopoietic progenitor cells could reduce the latent period of lymphoma relative to VavP-BCL2 alone when transplanted into recipient mice." (PMID 32695674, 2020). "In our study, we found that the KMT2D expression of patients with the mutation was higher than that of patients with wild type, suggesting that KMT2D might be an oncogene in NKTCL lymphoma." (PMID 32695399, 2020). "Thus, haploinsufficiency of Crebbp and Kmt2d cooperates in promoting the expansion of abnormal GCs, recapitulating a preneoplastic phenotype that typically precedes overt tumor formation in most genetically engineered mouse models of human lymphomas." (PMID 36893259, 2023). "In addition, Kmt2d deletion in CD19+ early B cells induced spontaneous lymphoma in 58% of mice." (PMID 34194626, 2021). "A recent study identified interaction between KMT2D and CREBBP, providing explanation for the frequent co-selection of inactivating both chromatin regulators in lymphoma." (PMID 40504770, 2025). "The data reveal that impaired KMT2D and enhanced EZH2 activity have quite distinct effects on the lymphoma epigenome." (PMID 40512686, 2025). "Therapeutically targeting KMT2D holds promise, as emerging preclinical data suggests KDM5 inhibitors may restore H3K4 methylation and suppress tumor growth in KMT2D-mutant lymphomas." (PMID 41008827, 2025). "In our study, we included KMT2D, CREBBP, EZH2, EP300, MEF2B, and TET2 in our lymphoma panel." (PMID 31403034, 2019). "While some of the affected genes such as ATM, CCND1, and KMT2D are known to be mutated in MCL, a large subset has not been reported as mutated before in this lymphoma but mutated in other types of lymphoma, as detailed in the Results section." (PMID 31334109, 2019). "CREBBP, KMT2D, and EZH2 are thus frequent epigenetic hits, initially considered as direct tumor inducers regulating B-cell proliferation and differentiation, but now widely recognized for their additional role as modulators of lymphoma TME, in particular based on the data obtained in GEMM." (PMID 38022603, 2023). "However, the panel targeted the most relevant genes for lymphoma diagnosis but did not cover all exons for some genes (e.g., KMT2D) and lacked a few select genes (e.g., FAS, SLAMF1, SPEN, and NCOR2), which are described in cutaneous MZL10,32." (PMID 37081015, 2023). "Moreover, KMT2D positively regulates the enhancer of the tumor suppressor gene IGFBP5 for melanoma suppression and the enhancers of several tumor suppressor genes (e.g., Socs3, Asxl1 and Arid1A) for lymphoma suppression." (PMID 34194626, 2021). "Similarly, KMD-5is restore expression of KMT2D- and CREBBP-regulated genes in KMT2D-mutant lymphomas, suggesting that these agents may have similar effects in the immune system." (PMID 35071240, 2021).
lymphoma (continued). "While the disease was not quite comparable to human lymphomas (e.g., FL and DLBCL), the results do support a role for KMT2D as a tumor suppressor." (PMID 33277464, 2020).
breast carcinoma (32 papers, 2014 to 2025). "We have created a set of four MCF10A cell lines to reconstitute the association between two genetic alterations found in breast cancer, the activation of PI 3-kinase by the H1047R mutation, and the inactivation of KMT2D." (PMID 38786098, 2024). "Some studies have indicated that low KMT2D transcript levels or decreased BTG1 protein expression are associated with poor survival in breast cancer." (PMID 37650999, 2023). "In breast cancer cell line-derived xenografts, deficiency of KMT2D was correlated with improved prognosis in model animals." (PMID 35477537, 2022). "While there is not enough scientific evidence to relate these alterations to endocrine therapy sensitivity, our group demonstrated that loss of KMT2D sensitizes breast cancer further to PI3K inhibitors through the downregulation of the ER signaling cascade." (PMID 35774123, 2022). "In this study, we evaluated the mutational status of genes involved in epigenetic control in breast cancer, identifying KMT2D as mutated in around 6% of triple negative tumors and linked with a particular detrimental prognosis." (PMID 30990809, 2019). "Here, we demonstrate that combined therapeutic targeting of PI3K/AKT and the H3K4 methyltransferase MLL1 decreases H3K4me3 to reduce transformative properties of human breast cancer cell lines and tumor growth in murine models, which is further enhanced following genetic loss of KMT2D/MLL4." (PMID 36970726, 2022). "Similarly, Azim and colleagues reported a higher frequency of KMT2C variants in elderly breast cancer patients as well as higher frequencies of KMT2D, another member of the lysine methyltransferase family." (PMID 34944094, 2021). "Given the close homology between KMT2C and KMT2D, we examined whether loss of KMT2D would have similar effects on the proliferation of ER+ breast cancer cell lines." (PMID 29755131, 2018). "Additionally, we identified the alterations of epigenetic targets, such as SWI/SNF related genes (SMARCA2, SMARCA4, SMARCA5) or histone modifiers (KMT2C or KMT2D), breast cancer-associated oncogenes (MYCN or MAPKs), or genes that are involved in drug-resistance (ESR1 and PIK3CA/B)." (PMID 31216647, 2019). "KMT2C and KMT2D are histone methyltransferases responsible for the monomethylation of H3K4 and are frequently mutated in cancer, such as breast cancer." (PMID 40032852, 2025). "The Kaplan–Meier survival analysis showed a significant association between elevated expressions of KMT2D and YBX1 and poor survival of breast cancer patients within this cohort." (PMID 38967349, 2024). "Other genes that were frequently mutated in breast cancer included KMT2C, KMT2D, and ARID1A, which were involved in epigenetic regulation." (PMID 38539518, 2024). "Collectively, these findings indicate that the levels of KMT2D and YBX1 are associated with the levels of c‐Myc and SENP1, suggesting a poor prognosis for individuals with breast cancer." (PMID 38967349, 2024). "It has also been reported that AKT interacted with and phosphorylated KMT2D, which downregulated KMT2D activity in ER-dependent gene transcription in breast cancer." (PMID 39025450, 2024). "Given the fact that H3K4me1 is mainly catalyzed by KMT2D in mammals, we next explored the roles of KMT2D in breast cancer cells." (PMID 38967349, 2024). "TNBC with increased SD on PrecontrastT1 showed a 23-fold, 13-fold, sevenfold, fivefold, and fivefold upregulation of CLEC3A, SRGN, HSPG2, KMT2D, and VMP1 respectively, and these genes are associated with poor survival in breast cancer." (PMID 37391754, 2023). "PI3Kα inhibition was found to enhance ER transcription by dephosphorylating and releasing KMT2D activity in breast cancer cells, which leads to a rationale for targeting the epigenome and PI3K signalling." (PMID 35604910, 2022).
breast carcinoma (continued). "We show that combined PI3K and MLL1 inhibition synergizes to cause cell death in in vitro and in vivo models of HR+ breast cancer, which is enhanced by the additional genetic ablation of the H3K4 methyltransferase and AKT target KMT2D/MLL4." (PMID 36970726, 2022). "We have also shown that FOXA1 binding profiles are influenced by the SWI/SNF complex and the histone methyltransferase KMT2D in breast cancer, suggesting a possible role for the chromatin landscape to evoke further differences in DNA binding for FOXA1." (PMID 35774123, 2022). "In in vitro cell line experiments, knockdown of KMT2D reduced the proliferation and invasion of pancreatic and breast cancer cells." (PMID 35477537, 2022). "A study using estrogen receptor (ER)-positive breast cancer cell lines showed that KMT2D knockdown reduced cell viability and increased the sensitivity of xenograft tumors to a PI3Kα inhibitor." (PMID 34194626, 2021). "We have also reported that KMT2D activates gene expression by upregulating H3K4me3 at gene promoters in breast cancer cells and in the neuron-committed human embryonal carcinoma cell line NT2/D1." (PMID 34194626, 2021). "A recent study indicated that treatment with the PI3Kα inhibitor induced an adaptive enhanced ERα signaling by activating KMT2D, a H3K4 methyltransferase in ER+ breast cancer cells with PIK3CA mutation, indicating therapeutic resistance to PI3Kα inhibitor." (PMID 34131114, 2021). "Treatment with Alpelisib in ER+ breast cancer cells or patients with primary tumors resulted in activation of ERα via lysine methyltransferase 2D (KMT2D)-dependent FOXA1-PBX1 complex." (PMID 33801659, 2021). "Recent data suggest that KMT2D is involved in the recruitment and activation of relevant breast cancer genes including FOXA1, PBX1, and ER." (PMID 30990809, 2019). "Whole exome sequencing (WES) detected multiple somatic variants in CTCs; some were in chromatin modeling factors KAT6B, KMT2D and KDM6A genes which are frequently mutated in breast cancer." (PMID 31003475, 2019). "We expressed shKMT2D in a representative panel of breast cancer cell lines resulting in approximately 50–70% knockdown of KMT2D mRNA." (PMID 29755131, 2018). "However, published reports suggest that the MLL enzyme MLL4/KMT2D is an AKT substrate, and its enzymatic activity is associated with resistance to the PI3K inhibitor alpelisib in HR+ breast cancer via epigenome-driven upregulation of ER signaling." (PMID 36970726, 2022). "Collectively, these data suggest that the therapeutic targeting of MLL1- and KMT2D/MLL4-directed H3K4 methylation may be beneficial HR+, PIK3CA-mutated, breast cancer." (PMID 36970726, 2022). "In this regard, it was recently reported that the homeobox (HOX)-containing gene HOXC6, a critical player in mammary gland development and milk production, is transcriptionally activated via coordination of KMT2D and ER in an estrogen environment in breast cancer and placental choriocarcinoma cells." (PMID 24633898, 2014). "The expression levels of KMT2D and YBX1 were both upregulated in tumour tissues and correlated with poor prognosis for breast cancer patients." (PMID 38967349, 2024). "In order to assess the clinical significance of KMT2D and YBX1 in breast cancer, we used a tissue microarray containing 140 breast cancer tissues and 77 adjacent healthy tissues." (PMID 38967349, 2024). "Collectively, these findings suggest that knockdown of KMT2D and YBX1 impairs breast cancer growth and metastasis." (PMID 38967349, 2024). "KMT2D‐mediated H3K4me1 mark and YBX1 were colocalized at the TSS and promoter regions of the c‐Myc and SENP1 genes in breast cancer cells." (PMID 38967349, 2024).
breast carcinoma (continued). "The use of AAV vectors to knockdown KMT2D and YBX1 in the mammary glands of MMTV‐PyMT transgenic (MMTV‐KMT2D‐KD or MMTV‐YBX1‐KD) mice enabled us to test their therapeutic potential in breast cancer." (PMID 38967349, 2024). "Targeting the MLL1 and/or the MLL4/KMT2D COMPASS complexes to reduce promoter or enhancer H3K4 methylation, respectively, impairs HR-positive breast cancer cell and tumor growth." (PMID 37568822, 2023). "Next, we investigated the roles of KMT2D and YBX1 using mouse models of breast cancer." (PMID 38967349, 2024). "Furthermore, the levels of SENP1 and c‐Myc showed a positive correlation with KMT2D and YBX1 in the breast cancer tissues analyzed as well as 17 TNBC tissues in this cohort." (PMID 38967349, 2024). "Therefore, we predict that mutations at the amino terminus of KMT2C and KMT2D SET domains might result in the truncation of the SET domain or loss of function of KMT2C and/or KMT2D methyltransferases, subsequently contributing to breast cancer initiation and progression." (PMID 25537518, 2015).